CRP (C-reactive protein)
Diseases named in the same sentence as CRP in open-access papers (continued):
Sharing a sentence is not in itself a finding about the gene and the disease.
Obesity (continued). "In the current study, adjusting for BMI and CRP reduced the OR for asthma associated with high soft drink consumption by 10% (from 2.60–2.33), suggesting that the association between soft drink and asthma was partly mediated by inflammation and obesity." (PMID 30871131, 2019). "Obesity was positively associated with IL-6 and CRP at all ages, in both sexes (p<0.001)." (PMID 31071114, 2019). "These salivary biomarkers correspond well to the established circulating plasma biomarkers associated with obesity, reflecting the metabolic aspect (e.g., insulin and leptin) as well as the inflammatory aspect (e.g., CRP and adiponectin) of the mechanism underlying obesity." (PMID 31236292, 2019). "Moreover, both obesity and CRP levels were independent risk factors for 1-year mortality in CAP patients." (PMID 31291389, 2019). "Obesity as well as BMI and waist circumference are associated with CRP levels." (PMID 31093012, 2019). "Obesity is associated with a low-grade chronic systemic inflammatory state characterized by elevation of acute-phase proteins such as C-reactive protein (CRP) produced by the liver and IL-6, secreted by adipocytes and adipose tissue macrophages, as well as by an increase in TNF-α by adipose tissue." (PMID 31885787, 2019). "Notably, increased IL-6 levels in obesity have been linked with metabolic inflammation, insulin resistance, and elevated circulatory CRP levels." (PMID 31718015, 2019). "Obesity, is associated with low grade inflammation and these physiological changes have in several studies been shown to be associated with elevated C-reactive protein (CRP) and homocysteine (Hcy) and to low concentrations of retinol among overweight/obese individuals." (PMID 29643928, 2018). "Conversely, obesity-parameters, s-glucose and HbA1C were positively associated with hs-CRP." (PMID 29813131, 2018). "Elevated serum CRP levels have been associated with obesity and systemic inflammation in MetS." (PMID 30186371, 2018). "However, this is the first reported association of high fractalkine in the omentum and high serum CRP in obesity-associated cancer." (PMID 30150990, 2018). "In obesity, elevated CRP levels are associated with more severe metabolic derangements." (PMID 30114262, 2018). "However, hs-CRP is independently associated with obesity, and some studies have found that the increased CRP levels in those with OSA are explained by obesity." (PMID 30402295, 2018). "The fact that that we found the same direction of the association between obesity/adiposity with IL-6 as well with CRP reinforces our findings in this cohort; moreover, the inverse association between adiposity with adiponectin also shows the consistency of this study." (PMID 29704817, 2018). "Due to the ongoing epidemic of obesity in Brazil, the objective of this study was to assess in a cross-sectional and in a prospective way the association of different obesity measurements (BMI, WC and % FM) and IL-6, CRP and adiponectin at 22 years, in a population Birth Cohort in Southern Brazil." (PMID 29704817, 2018). "Circulating high-sensitive CRP (hs_CRP) is a widely accepted marker of chronic low-grade systemic inflammation, and it has been associated with heart disease, colorectal cancer, and complications of diabetes and obesity." (PMID 30005082, 2018). "Evidence shows that CRP levels greater than 10 mg/L in obesity have been documented and may be associated with overweight/obesity." (PMID 29618342, 2018). "Although previous studies have demonstrated elevated CRP levels in obesity, the possibility of obesity associated co-morbidities contributing to this elevation could not be excluded." (PMID 29910808, 2018). "Inflammatory markers associated with insulin resistance and obesity, such as interleukin-6 and C-reactive protein (CRP), may also contribute to functional decline by causing negative changes in the regulation of skeletal muscle homeostasis." (PMID 30032324, 2018).
Obesity (continued). "Obesity is also associated with increased concentrations of acute-phase reactants such as CRP and fibrinogen which might further explain the increased risk of thromboembolism in patients treated with bariatric surgery." (PMID 29222767, 2018). "It is unknown whether the co-presence of obesity and loneliness is associated with additional risk for clinically elevated CRP." (PMID 30439985, 2018). "The linear regressions showed that overweight and obesity were associated with significantly elevated levels of CRP, TCL, thrombocytes, leukocytes, neutrophils, lymphocytes, monocytes, eosinophils, basophils, erythrocytes, ferritin, haemoglobin, fasting glucose and ALT." (PMID 29942512, 2018). "This inconsistency, and the many pregnancy independent factors (i.e. obesity) that can influence CRP levels, underlines a need for caution and continued research prior to drawing mechanistic conclusions about the role any of these mediators play in successful conclusion of pregnancy." (PMID 28636613, 2017). "T2D commonly associates with the metabolic syndrome in which obesity, elevated levels of triglycerides, low levels of high-density lipoprotein cholesterol, hypertension, and low-grade inflammation (reflected by an increase in CRP levels) are involved." (PMID 29184539, 2017). "That adiposity was positively associated with CRP may seem unsurprising given the well-known relationships between obesity and inflammation." (PMID 28003312, 2017). "In a cross-sectional study on 2266 randomly selected samples in Greece, those who reported “high” education had 45% lower CRP, but the association was mainly explained by the adoption of an unhealthy lifestyle, such as increased smoking habits, physical inactivity, and obesity." (PMID 28865434, 2017). "These elevations in cardiovascular risk factors during pregnancy are further worsened in clinical states such as gestational diabetes, pre-eclampsia or obesity, which are associated with a poorer lipid profile, insulin resistance and elevated high-sensitivity CRP, IL-6 and TNF-α." (PMID 28193219, 2017). "Furthermore, obesity confers a proinflammatory status and leads to increased CRP levels, an acute phase protein predictor of CVD risk." (PMID 29033897, 2017). "In addition, choline deficiency is associated with increased levels of several inflammatory markers that link obesity to obesity-associated diseases, including CRP, homocysteine, IL-6, and TNF." (PMID 28403191, 2017). "The lack of association between CRP and metals may have been because the majority of the study population (61%) was of normal BMI, and CRP concentrations are tied to obesity-linked chronic inflammation." (PMID 28789684, 2017). "Obesity in patients was associated with a marked increase in IL-6 and CRP levels." (PMID 28103807, 2017). "Obesity is associated with a state of low-grade inflammation, including increments in serum CRP." (PMID 28725447, 2017). "In addition, a strong positive association has been found between measures of obesity, such as waist circumference and BMI, with CRP." (PMID 28487812, 2017). "An increase in CRP levels was associated with an increased risk of colorectal adenoma only before BMI was taken into account, suggesting that the observed association can be ascribed to obesity-related inflammation." (PMID 28667300, 2017). "Higher serum levels of MDA and CRP have been previously reported in obesity and metabolic syndrome and have also linked obesity to alterations in the lipoprotein particles profile as well as to increased lipid peroxidation, during which the MDA is one of the most abundant products formed." (PMID 28555008, 2017). "Contrasting associations of serum leptin and CRP with cancer mortality may indicate sex‐specific biological or environmental pathways linking obesity and cancer in men and women which warrant mechanistic investigations." (PMID 26632325, 2016).
Obesity (continued). "In contrast, having CRP levels stable over time above 3 mg/L is considered to be chronic low-grade inflammation which contributes to the risk for development of metabolic diseases like cardiovascular diseases, Type 2 diabetes (T2D), and obesity." (PMID 27022211, 2016). "Although other causes such as colonization of lung by bacteria, smoking, obesity, air pollution due to increased production of interlukine-6 may also stimulate CRP production in patients with stable chronic airway diseases like COPD and asthma." (PMID 26958331, 2016). "CRP, a major acute-phase protein associated with chronic systemic inflammation, has been associated with obesity (particularly abdominal adiposity) and insulin resistance and may predict coronary heart disease risk." (PMID 27187457, 2016). "Although individuals with both metabolic abnormalities and obesity were at the highest risk of CRP and steatosis, the presence of metabolic abnormalities or obesity alone was associated with an almost 2-fold higher risk of vascular inflammation as well as a 3–5 fold risk of steatosis, respectively." (PMID 25838943, 2015). "Primary outcomes were obesity-associated hormones relevant to oesophageal adenocarcinoma risk (circulating concentrations of leptin, adiponectin, interleukin-6, tumour necrosis factor-alpha, C-reactive protein, and insulin resistance [HOMA])." (PMID 25706622, 2015). "Indeed, both obesity and aging are associated with pro-inflammatory states where high levels of C-reactive protein, IL-6 and TNF were found in the blood." (PMID 26604973, 2015). "Interestingly, GGT was significantly associated with CRP, a marker of systemic inflammation and associated with obesity, linking hepatocellular injury to systemic inflammation." (PMID 26269425, 2015). "Others molecules associated with obesity are CRP, adiponectin, and leptin." (PMID 26380303, 2015). "In addition, in CKD patients, obesity is associated with inflammation and metabolic syndrome, and a high BMI is strongly associated with C-reactive protein (CRP) levels." (PMID 24454716, 2014). "Association between salivary CRP and obesity has been reported in black South African children." (PMID 24915044, 2014). "Recently, obesity has been associated with elevated fibrinogen and CRP levels." (PMID 24957141, 2014). "This interpretation is supported by observations that deny an association between CRP level and history of atrial fibrillation, but confirm that CRP is elevated during episodes of atrial fibrillation or due to coexistence of hypertension or obesity." (PMID 25037974, 2014). "We have also indentified one molecular form (CRP mf-4) which is strongly linked to human obesity." (PMID 25299074, 2014). "Previous data on obesity, a condition usually linked with insulin-resistance and low chronic inflammation, revealed that circulating levels of sCD163 mirrored particular inflammatory markers such as CRP and TNFα." (PMID 24978196, 2014). "In addition, obesity is associated with a chronic low-grade inflammation as depicted by increased plasma levels of C-reactive protein (CRP), proinflammatory cytokines, and osteopontin as well as lower circulating levels of vitamin D (Vit D)." (PMID 24963291, 2014). "CRP is also associated with an increased risk to develop colorectal, cervical, and ovarian cancer, which are cancers that have been associated with obesity." (PMID 23819063, 2013). "Furthermore, food security status was also significantly associated with concentrations of HbA1c and C-reactive protein among all adults as well as with BMI and obesity among women." (PMID 24309090, 2013). "The association observed between red meat and hs-CRP is dependent on obesity." (PMID 22426755, 2013). "Other risk factors include obesity, low physical activity, hyperhomocysteinemia, high lipoprotein (a) or fibrinogen levels, mental stress, depression, and other novel risk factors such as high-sensitive C-reactive protein (CRP) levels." (PMID 24293786, 2013).
Obesity (continued). "Obesity is a low-grade inflammatory state that associates with increased secretion of several proinflammatory cytokines, such as tumor necrosis factor-α and interleukin-6, which stimulate CRP production." (PMID 24634792, 2013). "We assessed cross‐sectionally and longitudinally the association of high‐sensitivity (hs)‐CRP levels with overweight/obesity and related cardiometabolic risk factors in the Identification and prevention of Dietary‐ and lifestyle‐induced health Effects in Children and InfantS (IDEFICS) cohort." (PMID 23744403, 2013). "As IL-6 is produced and secreted from adipose tissue, which in turn stimulates CRP production from the liver, one would expect elevated levels of both indicators in the presence of obesity, increasing the likelihood of significant associations with clustered cardiometabolic risk." (PMID 23984329, 2013). "Further research with attention to obese patients might ascertain presumable correlations of IL-6 and CRP with adipokines as well as adiponectin, which are commonly related to obesity-associated pathologies." (PMID 24023413, 2013). "In one study, it was reported that elevated levels of CRP (≥3 mg/L) may increase the risk of metabolic syndrome mediated through obesity and factors related to insulin resistance." (PMID 23690772, 2013). "Of note, CRP seems to be more strongly associated with obesity than IL-6." (PMID 23781331, 2013). "It is suggested that CRP may be a reflection of the inflammation caused by smoking, obesity, metabolic syndrome, and other classical cardiovascular risk factors." (PMID 22505888, 2012). "Obesity is associated with greater susceptibility to infections, and therefore obesity-associated increase in frequency of infection may contribute to obesity-associated recurring increases in CRP." (PMID 22558327, 2012). "Research on the roles that C-reactive protein (CRP) and other risk factors such as cortisol and obesity play in the diagnosis of cardiovascular disease (CVD) in African and Caucasian women has become increasingly imperative when one considers the prevalence of hypertension in these groups." (PMID 22447476, 2012). "In summary, our results in the population from Southwestern Mexico indicate that the variation in the CRP gene is associated not only with basal levels of CRP, but also with other disorders such as obesity and T2D, and an association was found with genotype TT of rs1130864 and haplotype 7 (TGGG)." (PMID 23049543, 2012). "CRP and cortisol have been associated with an increased prevalence of hypertension and obesity." (PMID 22447476, 2012). "Resistin is associated with elevated CRP and white blood cells, suggesting that the role of resistin may be a component of obesity-related inflammation." (PMID 22567283, 2012). "We explored whether the association between obesity and CRP/SAA in breast cancer survivors differs by modifiable lifestyle factors, such as weight change, or use of NSAIDs." (PMID 22873489, 2012). "Moreover, an increase in CRP levels was greater in women than men in the obesity and higher fasting glucose category, and this association was more pronounced in women." (PMID 21663637, 2011). "A number of biomarkers (e.g., C-reactive protein, tumor necrosis alpha) or pathomechanisms (e.g., endothelial dysfunction and dyslipidemia) that have been shown to be associated with both overweight/obesity status and preeclampsia support this evidence." (PMID 22263114, 2011). "An increase in CRP was also reported to be associated with obesity." (PMID 21806828, 2011). "However the relationships between inflammation (as presumptively measured by CRP) and the traits associated with obesity and cardiovascular risk are of particular interest." (PMID 21943158, 2011). "Interestingly, like in the case of obesity and insulin resistance, the effect of CRP and IL-6 on the amylin-MetS association was rather minor." (PMID 21935471, 2011).
Obesity (continued). "Consequently, a strong positive association has been found between measures of obesity, such as waist circumference (WC) and body mass index (BMI), with CRP." (PMID 20617007, 2010). "Traditional risk factors, particularly obesity, are also associated with CRP." (PMID 21078191, 2010). "CRP, which is produced by the liver and typically rises as a part of the immune system's inflammatory response, has been gaining favor as a marker for hypertension and heart disease risk-- both known complications of obesity." (PMID 20170522, 2010). "Therefore, the association among CRP, insulin resistance and obesity was analyzed in Chinese patients with type 2 diabetes." (PMID 21167068, 2010). "Furthermore, the distribution of CRP and the relationship between CRP and obesity vary according to race and gender, with certain minority groups having greater risks associated with CRP." (PMID 20617007, 2010). "Moreover, there is a positive correlation between IL-6 levels and circulating CRP, thus increased levels of IL-6 in obesity can directly or indirectly contribute to the risk to develop multiple chronic diseases." (PMID 19545451, 2009). "Indeed, CRP is related to many other risk factors, such as obesity, smoking and socioeconomic adversity, as well as other “novel” risk factors such as fibrinogen and interleukin-6." (PMID 18714381, 2008). "This might reflect that the underlying determinants of CRP formation such as obesity or proneness to low-grade inflammation are hereditary, but may also be the result of a more direct influence of genes on CRP production." (PMID 18384670, 2008). "Obesity is associated with high levels of adiposity, significantly increased levels of adipokines such as leptin and elevated levels of the inflammatory marker C-reactive protein (CRP)." (PMID 18275595, 2008). "Obesity in humans is associated with increased insulin resistance, high blood pressure and high levels of C-reactive protein, and could explain the observed effects on risk factors." (PMID 17081292, 2006). "Furthermore, other conditions and indicators of high CHD risk such as family history of CHD, obesity, physical activity, income, education, and levels of C-reactive protein, triglycerides and Lp(a), for example, were unavailable." (PMID 15327691, 2004). "However, obesity and smoking, which are associated with deprivation, are also known to be associated with elevated C-reactive protein concentrations." (PMID 15305191, 2004). "Overweight and obesity increased adiposity may enhance a proinflammatory microenvironment through increased production of adipokines such as leptin, visfatin, and resistin, which have been linked to elevated CRP, TNF-α, and IL-6 levels." (PMID 41517610, 2026). "Furthermore, there is evidence that CRP plays a causal role in obesity." (PMID 40001459, 2025). "The results of this study elucidate the relationships between perceived family support, peripheral CRP and BMI and highlight the protective role of family support in moderating inflammatory processes, particularly in outpatients with schizophrenia who have a metabolic risk associated with obesity." (PMID 40724779, 2025). "In addition to age, sex and obesity indices, we observed direct associations of glucose, insulin, liver enzymes, CRP, and blood pressure with EAT thickness suggesting that individuals with cardiometabolic risk factors may potentially have higher EAT thickness." (PMID 38796541, 2024). "Obesity has also been associated with the altered follicular fluid, the critical environment for oocyte development and granulosa cell steroidogenesis, with elevated concentrations of leptin, insulin, triglycerides, inflammation markers (e.g., lactate and C-reactive protein), and oxidative stress." (PMID 38455649, 2024).